CHAT (choline O-acetyltransferase)
Diseases named in the same sentence as CHAT in open-access papers (continued):
Sharing a sentence is not in itself a finding about the gene and the disease.
Anxiety (12 papers, 2015 to 2024). Intense feelings of nervousness, tension, or panic often arise in response to interpersonal stresses. "The preceding data demonstrate that VP ChAT neurons regulate both sensation of pain-like stimuli and associated anxiety- and depression-like behaviours." (PMID 37069246, 2023). "In addition to the modulation of pain thresholds, VP ChAT neurons are also implicated in regulation of anxiety- and depression-like behaviours in neuropathic pain mouse model." (PMID 37069246, 2023). "We observed that repetitive stimulation of VP ChAT neurons induced anxiety- and depression-like behaviours in naive mice; repetitive inhibition of VP ChAT neurons caused conditioned place preference and mitigated anxiety- and depression-like behaviours in SNI mice." (PMID 37069246, 2023). "Further investigations are needed to address the role of this group of ChAT neurons in modulation of pain-, anxiety-, and depression-like behaviours." (PMID 37069246, 2023). "It was previously shown that ChAT-IRES-Cre mice display normal anxiety level, drug-induced cataplexy or nicotine self-administration behavior relative to WT littermates." (PMID 35925937, 2022). "Recent studies have demonstrated that ChAT::cre rats display elevated levels of the vesicular acetylcholine transporter protein, as well as altered motor, anxiety and attentional task performance." (PMID 33239269, 2021). "The current findings show that, compared to their Wt siblings, Long-Evans ChAT::Cre+ rats exhibit altered baseline behavior, affecting gross locomotor function, anxiety-related behavior as well as some aspects of sustained attention." (PMID 31506825, 2019). "Through a series of tests, we also undertook anxiety profiling in ChAT::Cre+ versus ChAT::Cre− rats." (PMID 31506825, 2019). "Accompanying the hyperactivity in the VP ChAT circuit were depression- and anxiety-like behaviours." (PMID 37069246, 2023). "Although the long-lasting effects of multi-day repetitive stimulation or inhibition of the VP-BLA ChAT pathway effectively regulated anxiety- and depression-like behaviours, acute manipulation of VP neurons or the VP-BLA pathway was required to affect pain thresholds." (PMID 37069246, 2023). "In contrast to previous studies revealing that systemic administration of ChAT drugs exerts paradoxical effects on pain and depression- and anxiety-like behaviours, our data hint that inhibition of VP ChAT neurons and the VP-BLA ChAT projection provide potential strategies to treat these symptoms." (PMID 37069246, 2023). "Decreased latency to react to the threatening stimulus might reflect an increased anxiety in ChAT-Cre mice." (PMID 35925937, 2022). "Studies leveraging these genes have provided evidence for molecular-functional mapping, including the role of ChAT+ neurons in anxiety, nicotine sensitivity, and fear, as well as recent work identifying a role for Tac1+ neurons in spatial learning and motivated behavior." (PMID 36113428, 2022). "However, ChAT-Cre young mice didn’t have significative difference in anxiety in open field and elevated plus maze tasks." (PMID 35925937, 2022). "Taken together, use of multiple experimental paradigms revealed that the ChAT::Cre+ rat model displays spontaneous locomotion and adaptation to a novel, anxiety-evoking environment that differs from the baseline behavioral profile seen for non-transgenic littermate rats of a similar strain." (PMID 31506825, 2019). "On the contrary, multi-day repetitive stimulation of either VP ChAT neurons or their projections to the BLA led to hyperactivity in VP and BLA neurons, accompanied by anxiety- and depression-like behaviours." (PMID 37069246, 2023).
Anxiety (continued). "The present study demonstrate that acute inhibition of either the VP ChAT circuit or the VP-BLA projection alleviates not only mechanical and thermal hypersensitivity, but also anxiety- and depression-like behaviours in neuropathic pain." (PMID 37069246, 2023). "Our results reveal an alteration of the cholinergic system, evidenced by a decrease of ChAT, CHT and VAChT gene expression in the striatum of the mice, that was accompanied by mild social disturbances and a tendency towards anxiety." (PMID 35925937, 2022). "Another study revealed an alteration of ChAT, choline transporter (CHT), and vesicular acetylcholine transporter (VAChT) gene expression in the striatum of the transgenic ChAT(IRES)-Cre mice, which was accompanied by mild social disturbances and anxiety." (PMID 39737113, 2024). "Surprisingly, repetitive inhibition of VP ChAT neurons did not alleviate anxiety- and depression-like behaviours in chronic stress mouse models." (PMID 37069246, 2023). "Multi-day, repetitive inhibition of either VP ChAT neurons or the VP-BLA projection in SNI mice produced effects that outlasted the period of photo-inhibition, including attenuation of the hyperactivity of VP and BLA neurons and improvements in anxiety- and depression-like behaviours." (PMID 37069246, 2023). "Second, we found that VP ChAT neurons modulate non-ChAT neurons but, because of technique limitations, we did not address the exact role of these non-ChAT neurons in the modulation of pain-, anxiety-, and depression-like behaviours." (PMID 37069246, 2023). "Chronically stressed mice showed anxiety- and depression-like behaviours in EPM, OFT, FST, and TST without activation of VP ChAT and non-ChAT neurons." (PMID 37069246, 2023).
congenital myasthenic syndrome (9 papers, 2015 to 2023). Congenital myasthenic syndrome (CMS) is a group of genetic disorders of impaired neuromuscular transmission at the motor endplate characterized by fatigable muscle weakness. "In Old Danish Pointer dogs with congenital myasthenic syndrome, a G to A missense variant in exon 6 of the gene encoding choline acetyltransferase (CHAT) was identified as possibly causal." (PMID 38003185, 2023). "A number of studies have focused on the biochemical impact of mutations in ChAT that were identified in patients suffering from congenital myasthenic syndrome with episodic apnea (CMS-EA)." (PMID 30458023, 2018). "Several recessive mutations have been identified in human ChAT which cause congenital myasthenic syndrome associated with episodic apnea (CMS-EA)." (PMID 30458023, 2018). "ChAT mutations are linked to congenital myasthenic syndrome (CMS), a rare neuromuscular disorder." (PMID 34557490, 2021). "In congenital myasthenia those with CHAT or RAPSYN mutations tend to develop apnoeas but only require NIV during acute exacerbations whereas in other mutations e.g. patients with COLQ may develop nocturnal hypoventilation and require long term home NIV." (PMID 25933065, 2015). "Acetylcholine (ACh) is essential for neuromuscular transmission and its impaired synthesis by ChAT can lead to neuromuscular junction disorders such as congenital myasthenic syndromes in humans." (PMID 30458023, 2018).
depression (9 papers, 2017 to 2025). "Dysfunction of striatal ChAT interneurons has been implicated in numerous psychiatric disorders including schizophrenia, depression, and other mood disorders, yet we lack a complete understanding regarding the input architecture to ChAT interneurons and their role in modifying behavior." (PMID 29714166, 2018). "Estrogen deficiency by VCD decreases ChAT, BDNF, and BAG1 and consequently leads to cognitive decline and depression-related behaviors." (PMID 34698102, 2021). "Depression models of chronic restraint or learned helplessness, lead to decrease CHAT levels and its corresponding gene expression in the Hb of rats while CHAT knockout mice show anhedonia-like behaviors." (PMID 30319463, 2018). "We then tested the effects of a habenula-specific CHAT knockdown on depression-like behavioral phenotypes." (PMID 28420875, 2017). "The down-regulation of MHb cholinergic nAChRs as well as CHAT in a CRS animal model of depression and in humans with MDD is more likely to induce profound deficits in MHb–IPN synaptic transmission." (PMID 28420875, 2017). "Our data suggest that targeting VP ChAT-neuron-derived circuits may be a promising therapeutic strategy for the treatment of comorbid chronic pain and depression." (PMID 37069246, 2023). "Thus, although enhancement of the ChAT system confers analgesic effects, it may exacerbate comorbid depression in chronic pain." (PMID 37069246, 2023). "However, chronic stress-induced changes in the protein levels of ChAT and acetylcholine may cause maladaptive plasticity downstream of acetylcholine, such as dysregulation of JAK/STAT signaling, that can lead to symptoms related to depression." (PMID 29197398, 2017). "As literature frequently reports alterations in serum concentration of stress hormone and heart rate variability in rodent depression models, we next examined whether the VP-BLA ChAT pathway regulates these parameters." (PMID 37069246, 2023). "Downregulation of cholinergic signaling in the habenula, including decreased expression of the genes related to cholinergic signaling, such as ChAT, CHT, VAChT, CHRNA3, and CHRNB4, has been demonstrated in an animal model of depression and in suicide victims diagnosed with major depressive disorder." (PMID 30873055, 2019). "Here, we demonstrated that the expression levels of cholinergic signaling genes (CHAT, VACHT, CHT, CHRNA3, CHRNB3 and CHRNB4) were down-regulated in a chronic restraint stress (CRS) rat model of depression, in which rats display depression-like behaviors such as anhedonia and mood despair." (PMID 28420875, 2017).
ischemia (9 papers, 2013 to 2024). A hypoperfusion of the BLOOD through an organ or tissue caused by a PATHOLOGIC CONSTRICTION or obstruction of its BLOOD VESSELS, or an absence of BLOOD CIRCULATION. "A second key finding is that miR-155 activity in ChAT+ neurons in contrast reduced the initial extent of SC damage caused by ischemia/reperfusion." (PMID 35185466, 2022). "In the recovery phase after acute myocardial infarction, infarct size reduction by remote ischemic conditioning (RIC) in mice was associated with increased myocardial ChAT and CHT1 expression and with increased myocardial ACh 12–24 h after sustained ischemia." (PMID 38700468, 2024). "In the ischemia (p<0.001) and ranibizumab group (p<0.001) a decrease of ChAT+ amacrine cells was found, which was less prominent in the ranibizumab group." (PMID 28800629, 2017). "Counts revealed only few ChAT+ cells in the ischemia (2.2±0.6 cells/mm; p<0.001) and the ranibizumab groups (1.9±0.6 cells/mm; p<0.001), when compared to controls (8.9±1.3 cells/mm)." (PMID 28800629, 2017). "In the present study, MCAO reduced ChAT immunoreactivity in the CA1 region, indicating that the cholinergic input from the medial septum to the hippocampus was damaged after ischemia." (PMID 28408940, 2017). "Therefore, GA treatment may upregulate ChAT and VAChT by reducing the apoptosis of neurons, which could compensate for the reduced ACh levels in brains of 2VO model mice and may have facilitated recovery of their ischemia-induced memory function." (PMID 26391515, 2015).
schizophrenia (8 papers, 2015 to 2023). A major psychotic disorder characterized by abnormalities in the perception or expression of reality. "It has been found that disturbance in neuronal ChAT levels contributes to the mechanisms’ underlying development of certain neurodegenerative diseases such as Alzheimer’s or Huntington’s disorder, schizophrenia, or amyotrophic lateral sclerosis." (PMID 24854048, 2015). "We selected the D1, and ChAT expressing neurons as these cell types have each been associated with the negative and cognitive symptoms of schizophrenia, as opposed to the D2 system, which is targeted by antipsychotic medications, and thus the positive symptoms of schizophrenia." (PMID 31185023, 2019).
diabetes (7 papers, 2012 to 2025). "Another observation from our study was the reduction of body weight in the db/db-ChAT-tg mice in the early stage of diabetes, indicating that elevated ACh from the heart has other extra-cardiac effects as well." (PMID 33618724, 2021). "In summary, in db/db mice, we observed a decreased ChAT and M2AChR expression from the early stage of diabetes, indicating reduced ACh level and ACh-mediated signaling." (PMID 33618724, 2021). "To understand the mechanism by which CTS treatment reverses diabetes-induced decrease of cholinergic marker proteins in the hippocampus, we immunohistochemically analyzed ChAT-immunopositive neurons in the medial septum that mainly project to the hippocampal area." (PMID 23082896, 2012). "Additionally, reduced body weight in db/db-ChAT-tg mice at the early stage of diabetes may have partially contributed to improved cardiac function as well as altering the molecular mechanisms." (PMID 33618724, 2021). "Next, the levels of expression of NNCS components (M2AChR, AChE, CHT1, ChAT, VAChT) and GLUT-4 were determined at the three stages of diabetes." (PMID 33618724, 2021). "Previous studies pointed to the parasympathetic myocardial denervation (proven by immunohistochemistry, using ChAT as a marker), which was concomitant with sympathetic denervation, in STZ-induced diabetic rats 3 months, and even more pronounced 6 months after diabetes induction." (PMID 32927766, 2020). "However, considering that the cardiac function of db/db-ChAT-tg mice remained improved despite the body weight was similar to db/db mice at the later stage of diabetes, this suggests that changes in body weight may not play a major role in influencing the cardiac function of db/db-ChAT-tg mice." (PMID 33618724, 2021).
Sepsis (7 papers, 2017 to 2025). Sepsis is defined as life-threatening organ dysfunction caused by a dysregulated host response to infection. "The levels of ChAT were increased in sepsis groups compared with those in sham groups, while AchE exhibited lower expression in the brain tissues of septic mice than those of sham mice." (PMID 34512319, 2021). "In conclusion, we have shown here that enhanced vagus nerve tonic activity leads to an immunosuppressed phenotype in sepsis survivors due to increased numbers of ChAT+ T cells." (PMID 30237803, 2018). "In the present study, we show that the immunosuppressive effects of constitutive vagus nerve activation in sepsis surviving mice are mediated through an increased number of CD4+ ChAT+ T cells." (PMID 30237803, 2018). "Our results indicate a previously unrecognized vulnerability of basal forebrain cholinergic neurons among sepsis survivors, indicated by decreased numbers of ChAT-positive neuronal bodies in this area." (PMID 29326685, 2017). "ChAT immunostaining revealed that the number of ChAT-positive neurons in the basal forebrain was significantly reduced in sepsis survivors compared to sham controls (n = 5 per group)." (PMID 29326685, 2017). "In the basal forebrain of mouse sepsis survivors, the number of cholinergic [choline acetyltransferase (ChAT)-positive] neurons was significantly reduced." (PMID 29326685, 2017). "Additionally, elevated plasma choline acetyltransferase (ChAT) concentrations were observed in patients with sepsis, with the highest levels detected in those who succumbed to infection." (PMID 40821837, 2025). "Given roles of ChAT and AchE in the synthesis and degradation of Ach respectively, the different performance of ChAT and AchE in response to sepsis suggested the enhanced activation of cholinergic system by increasing the production but decreasing the degradation of Ach." (PMID 34512319, 2021). "Therefore, the apoptosis or low expression of CHAT of cholinergic neurons in sepsis means an inadequate perception of inflammation and downregulation of anti-inflammation by MVZ and CAP, which in turn overactivate immune cells and eventually accelerate inflammation storm." (PMID 33061821, 2020). "Inhibition of cerebral HMGB1 downregulated ChAT expression but resulted in increased expression of AchE, indicating that HMGB1 might be responsible for hyperactivation of the brain cholinergic system under sepsis." (PMID 34512319, 2021). "However, the expression of CHAT remained unchanged statistically in the septic groups except the MLA group, probably because cholinergic neurons were excited by the sensation of inflammation to synthesize ACh and transmit instructions in sepsis unless they were severely damaged in the MLA group." (PMID 39156045, 2024).
Huntington disease (6 papers, 2015 to 2022). Huntington disease (HD) is a rare neurodegenerative disorder of the central nervous system characterized by unwanted choreatic movements, behavioral and psychiatric disturbances and dementia. "Alterations in the catalytic activity of 69-kDa ChAT are found in a number of neurological disorders, including Alzheimer's disease (AD), amyotrophic lateral sclerosis and Huntington's disease." (PMID 29311808, 2017).